GSTO2 (glutathione S-transferase omega 2)
Diseases named in the same sentence as GSTO2 in open-access papers (continued):
Sharing a sentence is not in itself a finding about the gene and the disease.
tumor (8 papers, 2013 to 2025). "Since, the majority of TCC patients with GSTO1 or GSTO2 polymorphisms died, it would imply the anti-tumor role of AA in TCC progression." (PMID 24040330, 2013). "Reduced gene expression of GSTO2, SMAD4, and MT1M was also significantly associated with high-grade tumor histology (Gleason grade group ≥ 8) in NKX3-1-loss tumors." (PMID 38751776, 2024). "In recent years, the relationship between GSTO2 and tumor development has received more and more attention." (PMID 36688005, 2023). "There are 5 tumor-infiltrating immune cells (TICs) related to GSTO2 expression, as the analysis results showed." (PMID 36688005, 2023). "If such kind of regulation of GSTO2 expression also exists in TCC cells, GSTO1 or GSTO2 polymorphisms would presumably result in deficient DHAR activity, and lower ascorbic acid level (AA) in tumor." (PMID 24040330, 2013). "Upregulation of GSTO2 might enhance tumor cells’ ability to clear chemotherapeutic drugs, reducing treatment efficacy." (PMID 40171042, 2025). "Likewise, 2.2-fold higher expression of GSTO2 protein in tumor ccRCC in comparison with non-tumor tissue was found (p = 0.007)." (PMID 31861116, 2019). "Furthermore, we evaluated GSTO1-1 and GSTO2-2 expression in ccRCC and adjacent non-tumor tissue, as well as phosphorylation status of two important survival pathways, PI3K/Akt/mTOR and Raf/MEK/ERK." (PMID 31861116, 2019). "Up-regulated GSTO1-1 and GSTO2-2 in tumor tissue might contribute to aberrant ccRCC redox homeostasis." (PMID 31861116, 2019). "This DHAR activity of GSTO2 may be critical in the maintenance of ascorbic acid (AA) levels not only in normal, but also in the tumor cells." (PMID 24040330, 2013). "On the contrary, the functional relevance of the other GSTO2*A183G (rs2297235) polymorphism has not been fully ascertained, although it has been investigated in some studies focused on urinary arsenic concentrations and arsenic-related neoplasms." (PMID 40724836, 2025). "Furthermore, up-regulated GSTO1-1 and GSTO2-2 enzymes in ccRCC tumor tissue might contribute to aberrant redox homeostasis." (PMID 31861116, 2019). "An uncritical evaluation of the data from the literature may show that some studies find an increased risk of a certain type of neoplasia in the presence of GSTO1*A140D or GSTO2*N142D polymorphisms, while just as many studies do not find significant correlations." (PMID 40724836, 2025). "Gene silencing of Glutathione S-transferase omega 2 in HT-29 and HCT-116 cells significantly inhibited tumor growth and migration." (PMID 36688005, 2023). "GSTO2 and MT1M functions have not been reported as factors in PCa progression, whereas loss of SMAD4 function has been shown to drive tumor growth and metastasis." (PMID 38751776, 2024). "Our results showed significantly higher protein expression of GSTO1 and GSTO2 in tumor ccRCC tissue compared to non-tumor tissue." (PMID 31861116, 2019). "Increased expression of GSTO1-1 and GSTO2-2 was demonstrated in tumor compared to corresponding non-tumor tissue (p = 0.002, p = 0.007, respectively), while GSTO1 expression was correlated with interleukin-1β (IL-1β)/pro-interleukin-1β (pro-IL-1β) ratio (r = 0.260, p = 0.350)." (PMID 31861116, 2019). "In ccRCC tumor tissue, in comparison with the corresponding non-tumor tissue, increased expression of both GSTO1 and GSTO2 was determined." (PMID 31861116, 2019).
neurodegenerative disease (6 papers, 2012 to 2025). A disorder of the central nervous system characterized by gradual and progressive loss of neural tissue and neurologic function. "This study presents the first evidence that GstO2 has a protective function in TAF15-associated neurodegenerative diseases." (PMID 36411469, 2022). "Therefore, our findings suggest that GstO2 can be used as a therapeutic mediator to treat neurodegenerative diseases caused by TAF15." (PMID 36411469, 2022). "Taken together, our results indicated that GstO2 could be used as a novel therapeutic mediator for the treatment of neurodegenerative diseases caused by hTDP-43." (PMID 32674363, 2020).
infection (2 papers, 2018 to 2022). The state of being infected such as from the introduction of a foreign agent such as serum, vaccine, antigenic substance or organism. "Ces résultats suggèrent que la GSTO2 de F. hepatica joue un rôle important dans la modulation des fonctions physiologiques des macrophages, cette protéine pouvant être impliquée dans des rôles immunomodulateurs et anti-inflammatoires au cours de l’infection." (PMID 35315767, 2022).
neurological disorders (2 papers, 2024 to 2025). "Based on these findings, we hypothesize that RELN and GSTO2 may act as protective factors against the development of these neurological disorders." (PMID 40171042, 2025).
GSTO2 also shares sentences with these, for which no sentence is quoted: acute lymphoblastic leukemia (2 papers); Hypertension (2); breast tumor (1); cholangiocarcinoma (1); co-infection (1); frontotemporal dementia (1); germ cell tumor (1); head and neck cancer (1); leukemia (1); mantle cell lymphoma (1); Obesity (1); open-angle glaucoma (1); Pan (1); Parkinson's (1); retinal degeneration (1); spinocerebellar ataxia type 2 (1); thyroid cancer (1); transitional cell carcinoma (1).